INS (insulin)
Diseases named in the same sentence as INS in open-access papers (continued):
Sharing a sentence is not in itself a finding about the gene and the disease.
Obesity (continued). "As part of the adipose metabolic alterations, insulin is another obesity-related factor that induces the activity of adipose aromatase, while directly stimulating the growth and invasion of breast cancer cells." (PMID 31380268, 2019). "Ultimately, obesity leads to a down-regulation of the downstream signaling pathways of insulin, and the down-regulation of insulin signaling reduces glucose metabolism." (PMID 31311133, 2019). "Consistent with previous research, here we found that using the same HFD also successfully induced mice obesity and the related metabolic disorder, indicated by higher fat deposition, insulin resistance and hepatic steatosis." (PMID 31191487, 2019). "Still, mendelian randomization analyses have clearly shown a causal relationship of glucose-stimulated insulin secretion with body weight, according to the carbohydrate–insulin model of obesity." (PMID 31861591, 2019). "HIIT has been reported to improve obesity and obesity-related diseases by reducing abdominal visceral fat, maintaining or increasing fat mass, and improving metabolic function (insulin sensitivity) through greater stimulation of skeletal muscles." (PMID 32292722, 2019). "Mice deficient in Myd88, but not for TRIF, are protected from diet-induced obesity, suggesting that obesity and insulin resistance are controlled by different mechanisms." (PMID 30931309, 2019). "In both cases, transplanted adipocytes showed to diminish their size, and insulin sensitivity, as well as serum lipid profile, showed to be improved, correcting almost all the metabolic parameters altered by obesity." (PMID 31178685, 2019). "As expected, HFD time-dependently induced obesity, changes in body composition, and reduced glucose tolerance and insulin sensitivity." (PMID 30813929, 2019). "Neuroregulin 4 (NRG4), a ligand that specifically binds to ERBB4, has been reported to promote browning of white fat, fuel oxidation, prevention of high-fat diet-induced obesity, and improvement of insulin sensitivity." (PMID 31852448, 2019). "Mfn2, but not Mfn1, deletion in brown adipose tissue (BAT) remodels the mitochondrial dysfunction, leading to an increase in insulin sensitivity and resistance to obesity." (PMID 31551926, 2019). "In obesity, accumulated fat tissue, depending on the current metabolic status, is characterized by a different secretory profile, leading to disruption of insulin sensitivity and metabolic disturbances." (PMID 31195747, 2019). "It should be noted that a decrease in the intrahypothalamic leptin level in the agouti-mice was shown by us earlier, while a decrease in the intrahypothalamic insulin level in the melanocortin obesity was shown by us for the first time." (PMID 30870482, 2019). "In animal models of obesity, as well as in obese patients, FGF21 has been shown to induce body weight loss and to increase insulin sensitivity and lipid homeostasis." (PMID 31374856, 2019). "Several WNT10B SNPs have been associated with obesity, and WNT10B has been implicated in regulating insulin sensitivity via skeletal muscle cells, leading to improved insulin sensitivity." (PMID 31089877, 2019). "Obesity reduced WAT insulin/MAPK/mTORC1 signaling, which was partially reversed by exercising the obese dams." (PMID 31466137, 2019). "Under a pathological condition such as severe obesity, the adipose tissue synthesizes and secretes several pro-inflammatory cytokines, which aggravate insulin resistance and the systemic inflammatory status." (PMID 31405033, 2019). "Obesity involves increased adipose tissue, which results in high circulating levels of free fatty acids and inhibits insulin-stimulated glucose uptake." (PMID 31835508, 2019). "In the present study, we found that dietary CUR reduced the burden of diet-induced obesity in HFS mice by lowering circulating fasting insulin levels." (PMID 31372175, 2019).
Obesity (continued). "Obesity is accompanied by a large number of systemic changes, in addition to changes in insulin, with increases in IGF-activity, sex steroids, inflammatory cytokines, adipokines, angiogenic factors and metabolic fuels, including glucose, fats and cholesterol." (PMID 30809194, 2019). "Further, brief intravenous infusion of insulin in a pattern that mimics a CPIR during food ingestion improves glucose tolerance in people with obesity." (PMID 31877631, 2019). "By taking advantage of the approach, it was demonstrated that specific miRNAs, such as miR-802, play a vital role in obesity-related hepatic insulin insensitivity and when reduced in mice by the AMOs they regained normal metabolic function." (PMID 31482095, 2019). "Conversely, genetically altered mice in which insulin secretion is limited are resistant to HFD-induced obesity." (PMID 31315689, 2019). "LPS can bind and activate TLR-4 to increase the expression of pro-inflammatory mediators such as TNF-α, and these pro-inflammatory mediators can interfere with the binding of insulin to its receptor, leading to IR and obesity." (PMID 30744700, 2019). "The relation of weight dynamics and insulin sensitivity is well-described when intensive anti-obesity interventions are evaluated upon completion and their sustainability determined following a longer follow up." (PMID 31474943, 2019). "Regulatory T cells (Tregs) and resident anti-inflammatory (M2-like) polarized macrophages that produce factors such as IL-10 help to maintain insulin sensitivity but are reduced within the VAT during obesity." (PMID 30944419, 2019). "Obesity currently affects more than 600 million people worldwide by recent estimates and it was also characterized by defects of insulin action." (PMID 31803062, 2019). "During aging, CAR−/− male mice developed hypercortisism, obesity, glucose intolerance, insulin insensitivity, dyslipidemia and hepatic steatosis." (PMID 31882815, 2019). "Still, future research on the Nur77 and NOR1 response to insulin stimulation should utilize an age‐matched control group to better assess the impact of obesity or T2DM per se." (PMID 30912283, 2019). "The pathophysiological significance of ACs is complex, since, as stated in the Introduction, increased levels in plasma and tissues are observed in obesity and insulin resistant state, but also after weight loss and exercise." (PMID 31349613, 2019). "Hyperinsulinemia is a common feature in obesity, and insulin can promote proliferation in certain cell types." (PMID 31003943, 2019). "This abnormal secretion of pro-inflammatory cytokines leads to the impairment of insulin signaling in central and peripheral tissues, and subsequently, to the development of several other obesity-related comorbidities." (PMID 30967878, 2019). "Previous studies have showed that obesity induce impairment of insulin signaling, which can lead to bronchoconstriction, fibrosis, and AHR21,22." (PMID 31666643, 2019). "Pharmacological studies have demonstrated that FGF21 improves insulin sensitivity, thereby countering the development of metabolic diseases, including obesity and T2DM." (PMID 31121855, 2019). "Chronic JAK-STAT3 signaling induced by IL-6 leads to the increased expression of suppressor of cytokine signaling-3 that not only negatively regulates IL-6 signaling but also hinders insulin action, eventually resulting in obesity and IR." (PMID 32063863, 2019). "It has been shown in multiple large cohorts across various ethnic backgrounds and age groups that insulin sensitivity is negatively correlated with body mass index (BMI, a crude measure of the degree of obesity)." (PMID 31474943, 2019). "As early as 1986, it was found that saponins in M. charantia seeds ameliorated obesity by improving insulin sensitivity and glucose homeostasis." (PMID 31487939, 2019).
Obesity (continued). "Contributing factors to the pathophysiology of CKD in obesity include the activation of the renin-angiotensin-aldosterone system, increased sympathetic nervous activity, insulin resistance, and oxidative stress." (PMID 34466454, 2019). "Hall and colleagues tested the carbohydrate-insulin model of obesity by evaluating the impact of a protein controlled ketogenic diet after a high-carbohydrate baseline diet." (PMID 31726791, 2019). "Participants with obesity were less insulin sensitive (p < 0.0005) and tended to have a slower rate of insulin clearance (p = 0.09) than normal-weight participants." (PMID 31877631, 2019). "Both intramyocellular lipids and intermuscular adipose tissue increase in obesity and are negatively related to insulin sensitivity." (PMID 31040340, 2019). "Foxp1aP2∆/∆ knockout mice displayed similar phenotypes with Foxp1Ad∆/∆ mice, including resistance to HFD-induced obesity as well as improved glucose metabolism and insulin sensitivity after HFD feeding." (PMID 31699980, 2019). "In obesity, a wide range of inflammatory and stress conditions are often generated in liver and/or adipose tissue, among other insulin-targeted tissues." (PMID 31482095, 2019). "The mRNA level of vaspin is enhanced by increased fat mass, impaired glucose tolerance, and decreased insulin sensitivity observed in individuals with obesity and T2DM." (PMID 31208019, 2019). "While obese WT mice showed a marked reduction in Akt phosphorylation upon insulin treatment in both cardiac and hepatic tissue, Nlrp3−/− mice were protected against this obesity-induced effect." (PMID 31379826, 2019). "The authors proved that expression of this adipokine in rat adipocytes was high when obesity, animal body weight, and insulin levels peaked in the experiment." (PMID 30909620, 2019). "Mouse models demonstrate a clear effect of Cadm2 on obesity and gluco-metabolic parameters: A global Cadm2-knockout mouse demonstrated reduced body weight, improved insulin sensitivity and improved glucose tolerance." (PMID 31089183, 2019). "A recent study showed that obesity in mice stimulates hepatocytes to synthesize and secrete Dpp4, which promotes visceral adipose tissue inflammation and insulin resistance." (PMID 30824564, 2019). "The ability to metabolize the naturally occurring FXR antagonist tauro-β-muricholic acid is an essential process toward obesity, steatosis, as well as impaired tolerance to glucose and insulin." (PMID 30931309, 2019). "Insufficient mitochondrial capability to deal with nutrient excess in obesity has been suggested to produce lipid metabolites and ROS that interfere adversely with insulin signalling paths." (PMID 31195596, 2019). "Regarding its anti-diabetic and anti-obesity effects, some studies have been published on the beneficial role of ABG improving the lipid profile and insulin sensitization in an obesity and/or diabetes context, both in experimental animals and in humans." (PMID 30642033, 2019). "In conclusion, the AET prevented obesity and IR, reduced insulin signaling proteins and increased lipolysis signaling proteins in the SC-WAT." (PMID 31022246, 2019). "Obesity and inflammation-related stress responses in insulin-responsive tissues activate liver MAPKs, which are thought to impair insulin action and lipid metabolism." (PMID 31258478, 2019). "Equine metabolic syndrome (EMS) is a cluster of metabolic derangements, including insulin dysregulation (ID; insulin resistance and/or hyperinsulinemia), hypertriglyceridemia, obesity/regional adiposity, and laminitis." (PMID 31339945, 2019). "Recently it has become evident that interference with either JNK1 or IKK activity improves insulin signaling in mouse models of obesity and lipid-induced glucose intolerance." (PMID 31149020, 2019). "In the same way, it has been described that GSTA4 expression is downregulated in the adipose tissue from obese insulin-resistant C57BL/6 J mice and in humans with obesity-linked IR." (PMID 31049126, 2019).
Obesity (continued). "Both indices of adipose tissue IR (fasting and prandial) increased with the degree of obesity (p < 0.0001), while whole-body insulin sensitivity (WBISI) decreased with degree of obesity (p < 0.0001)." (PMID 30637483, 2019). "The resultant insulin and leptin resistance would likely result in unfavorable energy intake and expenditure and favor the development of obesity." (PMID 31141526, 2019). "The purpose of this in vitro study is to ascertain how high salt enhances obesity characteristics such as inflammatory response, insulin resistance, and what mechanism or signaling-pathways trigger adipogenesis." (PMID 30621146, 2019). "Msr have also been implicated with neurodegenerative diseases such as Alzheimer's and Parkinson's disease, auditory function and hearing loss, visual deterioration, and obesity, and insulin resistance." (PMID 31282614, 2019). "Instead, it evoked complex, interconnected changes in muscle and systemic metabolism leading to increased whole-body insulin sensitivity, increased muscle glucose uptake, and attenuation of obesity and T2D." (PMID 31305240, 2019). "The prevalence of obesity has increased dramatically since the introduction of intensified insulin therapy for people with T1D." (PMID 31687046, 2019). "Total body movement (counts/day) was significantly and independently associated with three of six risk factors (fasting triglycerides, insulin, and HDL) and with clustered metabolic risk after adjustment for age, gender, and obesity." (PMID 31331009, 2019). "In accordance with the theory linking obesity and IR, excessive accumulation of lipids in insulin-sensitive tissues (lipotoxicity), like liver, alters several cellular functions, including insulin signaling." (PMID 31771123, 2019). "Metabolic syndrome (MS) is defined by a constellation of multiple risk factors for T2DM and cardiovascular disease (CVD), including hyperglycemia, dyslipidemia, obesity, hypertension and impaired insulin sensitivity." (PMID 30972022, 2019). "Leptin levels are elevated in obesity, but leptin’s insulin sensitizing and anorexigenic effects are abrogated, due to resistance of target cells to the action of this hormone in this condition." (PMID 30823446, 2019). "In diet-induced obesity, metformin (MF) has weight-lowering effect and improves glucose homeostasis and insulin sensitivity." (PMID 30870482, 2019). "In spite of several reports that the levels of “metabolically favorable” molecules decrease with obesity and IR, few studies have investigated the impact of insulin on the AT secretion of adipokines and other molecules." (PMID 30754657, 2019). "Its name is derived from its ability to interfere with the action of insulin and is thought to be an important link between obesity and diabetes." (PMID 31053755, 2019). "It is reported that PTP1B‐knockout mice exhibit high level of insulin sensitivity and are also resistant to high‐fat diet‐induced obesity." (PMID 30680174, 2019). "Obesity is also associated with reduced transport of proteins across the BBB that act on the CNS to regulate feeding, such as leptin, insulin, and ghrelin." (PMID 30986918, 2019). "We assessed the degree of obesity, whole body composition, energy balance, plasma lipid profile and insulin sensitivity." (PMID 31689911, 2019). "Based on these genetic data, we found that multiple measures of obesity, as well as diastolic blood pressure (DBP) and fasting insulin, are associated with RCC risk." (PMID 30605491, 2019). "Some studies indicate that GLP-1 affects the secretion of Insulin and glucagon through related calcium signaling pathways to influence obesity." (PMID 31195699, 2019). "In contrast, blockade of VEGF-C and VEGF-D by overexpression of a soluble form of VEGFR-3 reduced macrophage infiltration and improved insulin sensitivity in diet-induced obesity." (PMID 30863410, 2019).
Obesity (continued). "LPI and oleoylethanolamide promote insulin release from isolated mouse islets, and in humans modulation of the LPI/GPR55 system has been positively linked with increased obesity by poorly understood mechanisms." (PMID 30148676, 2019). "PrAO-dependent activation of glucose uptake was negatively correlated with body mass index and reflected the decrease of insulin responsiveness of human fat cells with increasing obesity." (PMID 31409018, 2019). "There is controversy regarding the role of serum cC16:1 in health, as it increases insulin sensitivity in healthy subjects but has adverse effects in obesity." (PMID 31137678, 2019). "Obesity leads to high circulating concentrations of different hormones, such as insulin and leptin and low levels of the hormone adiponectin, all factors which have been described to increase the risk of advanced PCa." (PMID 31284686, 2019). "The circulating and adipose Ang II-ACE-AT1R axis is activated in obesity and closely correlates with BMI, adiposity, and insulin resistance." (PMID 31262355, 2019). "Although plasma insulin was also gradually increased during the development of HFD-induced obesity, there was a low correlation between basal norepinephrine and plasma insulin (r = 0.428, P = 0.009)." (PMID 31682617, 2019). "In females, positive correlations were found between serum L-carnitine level and obesity, serum TC level, serum glucose level, serum insulin levels, IR in females with normal fasting glucose levels, while none was found in those with hyperglycemia." (PMID 30972022, 2019). "The data provide evidence that Nur77 and NOR1 insulin responsiveness is blunted in obesity and T2DM, and that a lifestyle intervention involving aerobic exercise training partially recovers this response." (PMID 30912283, 2019). "In conclusion, despite the differences found among the populations, only obesity resulted in an increased chance that the pregnant woman needed insulin as a complementary treatment to metformin, while FG < 90 mg/dL and primiparity were protective factors." (PMID 31856288, 2019). "The present work demonstrated that honey has a protective effect in the development of obesity, maintaining insulin sensitivity, and low levels of serum glucose and insulin." (PMID 31010163, 2019). "Alternatively, T2D leads to obesity as the inherent insulin resistance increases glucose production and insulin levels, resulting in obesity." (PMID 30871285, 2019). "Body composition, ketosis, insulin sensitivity and myokines were evaluated in 79 patients with overweight/obesity after a therapy to lose weight with a VLCK diet, a LC diet or bariatric surgery." (PMID 31590286, 2019). "This study investigates how dietary CUR improves insulin clearance and maintains a proper range of circulating insulin level in the diet-induced obesity (DIO) mouse model." (PMID 31372175, 2019). "Both obesity per se, via the adipocytokine profile it induces, and low insulin sensitivity, are independent determinants of the adverse metabolic phenotype characteristic of the metabolic syndrome." (PMID 31474943, 2019). "Obesity is characterised by imbalanced bioenergetics that raise ROS generation sufficiently to impair muscle insulin signalling." (PMID 31195596, 2019). "Compared to the use of the metabolic syndrome criteria to sub-categorise obesity, fewer studies have used insulin sensitivity per se (that is, sub-categorisation into insulin-sensitive obesity (ObSen) and insulin-resistant obesity (ObRes))." (PMID 31071971, 2019). "Resistin is produced by WAT and brown adipose tissue, antagonizes insulin action, and is elevated in obesity." (PMID 31191366, 2019). "In obesity, IL-6 is released from the adipocytes and deteriorates insulin sensitivity of the tissues." (PMID 31438590, 2019). "Suppressor of cytokine signaling 3 (SOCS3) is another molecule responsible for hypothalamic insulin signaling induced by obesity." (PMID 30875909, 2019).